ARMH1 (armadillo like helical domain containing 1)
Synonyms: C1orf228; NCRNA00082; MGC33556; p40
Tractability: Antibody: its Gene Ontology location is reachable by antibodies, with high confidence; the Human Protein Atlas places it where antibodies can reach.
Gene: Protein-coding gene on chromosome 1 (44,674,692 to 44,725,591, forward strand). Ensembl gene ENSG00000198520.
Subcellular location (Human Protein Atlas): Cytosol; Plasma membrane
Gene Ontology:
Cellular component: cytosol; plasma membrane
Genetic constraint (gnomAD): Loss-of-function variants: 34 observed, 48.49 expected, observed/expected ratio (o/e) 0.7, 90% interval 0.53 to 0.93. The upper end of that interval is the gene's LOEUF score, 0.93, which puts it in group 3 of 6, group 1 being the genes least tolerant of losing a copy. Missense variants: 538 observed, 550.27 expected, observed/expected ratio (o/e) 0.98, 90% interval 0.91 to 1.05. Synonymous variants: 221 observed, 217.35 expected, observed/expected ratio (o/e) 1.02, 90% interval 0.91 to 1.14.
Homologues: Orthologues: chimpanzee ARMH1 (99% identical), macaque ARMH1 (96% identical), dog ARMH1 (83% identical), rabbit ARMH1 (82% identical), guinea pig ARMH1 (81% identical), pig ARMH1 (80% identical), rat Armh1 (78% identical), mouse Armh1 (77% identical), tropical clawed frog armh1 (55% identical).
Diseases named in the same sentence as ARMH1 in open-access papers:
ARMH1 is named in the same sentence as 8 diseases in open-access papers, as found by Europe PMC text mining. Sharing a sentence is not in itself a finding about the gene and the disease. The quoted sentences say what the papers report.
oral squamous cell carcinoma (2 papers, 2023 to 2024). "Recently, ARMH1 has been identified as a potential biomarker gene for the immunological score-based risk stratification signature in oral squamous cell carcinoma, but ARMH1 is still reported to be an unknown function gene and has not been studied in detail in cancer, especially leukemias." (PMID 39703843, 2024). "C1orf228, also called ARMH1, is a signature gene in oral squamous cell carcinoma based on random forest methods." (PMID 38074669, 2023).
acute leukemia (1 paper, 2024). A clonal (malignant) hematopoietic disorder with an acute onset, affecting the bone marrow and the peripheral blood. "These correlative analysis results provide substantial evidence for ARMH1 association with high-risk or aggressive pediatric acute leukemias, specifically AML." (PMID 39703843, 2024). "Additionally, publications from our group in characterizing T-cell acute lymphocyte leukemia (T-ALL) and Mixed Phenotype leukemia (MPAL) also depicted higher expression of ARMH1 in the leukemic cells as compared to normal cells, indicating its association with other acute leukemias." (PMID 39703843, 2024).
leukemia (1 paper, 2024). A malignant (clonal) hematologic disorder, involving hematopoietic stem cells and characterized by the presence of primitive or atypical myeloid or lymphoid cells in the bone marrow and the blood. "ARMH1 expression is also significantly correlated with the pediatric leukemia stem cell score of 6 genes (LSC6) associated with poor outcomes." (PMID 39703843, 2024). "Correlative analysis of ARMH1 expression with enrichment of blast cells, and leukemia risk scores depicted a significant positive association indicating ARMH1’s role in leukemogenesis." (PMID 39703843, 2024). "Perturbation of ARMH1 (knockdown and overexpression) in leukemia cell lines significantly impacted cell proliferation and migration." (PMID 39703843, 2024). "In summary, these findings provide preliminary evidence of ARMH1 involvement in mitochondrial fatty acid synthesis in leukemia cells." (PMID 39703843, 2024). "Bone marrow samples from 21 pAML patients were analyzed using single cell RNA sequencing, functional assays with ARMH1 knockdown and overexpression were performed in leukemia cell lines to evaluate impact on proliferation and migration, and chemotherapy sensitivity." (PMID 39703843, 2024). "Additionally, expression of ARMH1 in AML malignant cells from an external pediatric AML study was correlated with the enrichment of a leukemia stem cell score of 6 genes (LSC6) that predicts AML outcome reliably with high LSC6 scores associated with poor outcome." (PMID 39703843, 2024). "Further, correlative analysis of using AML data from TARGET cohort revealed ARMH1 expression has a significant correlation with CDCA7 (r=0.29, P<2.2e-16) and c-MYC (r=0.2, P=4.6e-16) which suggests intersection between their regulatory pathways in leukemia cells." (PMID 39703843, 2024). "Consequently, the conclusion of findings solely from in vitro or clinical studies may not capture the entirety of the pathobiological role of ARMH1 in pediatric leukemia." (PMID 39703843, 2024).
pediatric cancers (1 paper, 2024). "ARMH1, also known as C1orf228, has not been previously associated with AML or other pediatric cancers." (PMID 39703843, 2024).
cancer (2 papers, 2023 to 2024). A tumor composed of atypical neoplastic, often pleomorphic cells that invade other tissues. "Our data shows that ARMH1, a novel cancer-associated gene, is highly expressed in the malignant blast cells of multiple pediatric hematologic malignancies, including AML, T/B-ALL, and T/B-MPAL." (PMID 39703843, 2024).
ARMH1 also shares sentences with these, for which no sentence is quoted: autoimmune disease (1 paper); hematologic malignancies (1); pituitary tumor (1).